BCHE (butyrylcholinesterase)
Diseases named in the same sentence as BCHE in open-access papers (continued):
Sharing a sentence is not in itself a finding about the gene and the disease.
neurological disorders (23 papers, 2015 to 2025). "Inhibition of key enzymes implicated in neurological disorders, including AChE, BChE, beta-secretase and monoamine oxidase, has been identified as a promising approach towards developing neurotherapeutic agents." (PMID 40893584, 2025). "Butyrylcholinesterase (BChE) and acetylcholinesterase (AChE) hydrolyze butyrylcholine and acetylcholine neurotransmitters, respectively, reducing nerve transmission to the brain and causing neurological disorders." (PMID 41393958, 2025). "Based on the obtained in silico, experimental and computational results regarding biological activity in the present work, novel carbamates (structure B) represent potential selective BChE inhibitors as new therapeutics for neurological disorders." (PMID 39860186, 2025). "Based on the obtained in silico, experimental and computational results on biological activity in the present work, new carbamates 1 and 7 represent potential selective BChE inhibitors as new therapeutics for neurological disorders." (PMID 39860186, 2025). "miRNAs that target BChE mRNA are being regarded as biomarkers, especially in conditions such as inflammatory disorders, neurological disorders, and metabolic dysfunction." (PMID 40612057, 2025). "Due to its dual inhibition of AChE and BChE activities, hesperidin from Astragalus crenatus holds promise for the development of novel therapeutics aimed at neurological disorders, particularly AD." (PMID 38543134, 2024). "The related enzyme butyrylcholinesterase (BChE) is also involved in the regulation of the cholinergic system as a backup to AChE in hydrolyzing the neurotransmitter acetylcholine (ACh) in neurological disorders." (PMID 34832929, 2021). "In CR, 52 AD-related target proteins were validated to bind with 25 active ingredients, including ACHE, APP, BCHE, BCL2, BAX, CASP3, and CASP7, and are implicated in cell apoptosis and vascular and nervous system diseases." (PMID 32802132, 2020). "In the treatment of neurological disorders, potential inhibitors of acetylcholinesterase (AChE) and butyrylesterase (BChE) enzymes are of prime importance." (PMID 29295712, 2018). "being an unexplored member of Boraginaceae was investigated for GC/MS analysis, acetylcholinesterase (AChE), butyrylcholinesterase (BChE) inhibitory and antioxidant activities in an attempt to find its effectiveness in neurological disorders." (PMID 29169349, 2017). "Cholinesterases, including AChE and BChE, are esterases catalyzing the hydrolytic breakdown of neurotransmitter acetylcholine, and are hence involved in various neurological disorders, especially AD." (PMID 26798565, 2015). "Although the inhibition of AChE has been extensively studied as a symptomatic treatment in neurological diseases, less attention has been paid to its sister enzyme, butyrylcholinesterase (BChE), that co-regulates the metabolism of the neurotransmitter acetylcholine." (PMID 37047044, 2023). "This study highlights a potential perturbed mechanism in neurological disorders, such as PTSD, while contributing to the understanding of the function of BChE function in the human brain." (PMID 33061920, 2020).
infection (18 papers, 2009 to 2025). The state of being infected such as from the introduction of a foreign agent such as serum, vaccine, antigenic substance or organism. "Atypical BChE variants by interfering with the inflammatory response, increase susceptibility to infection, having compromised the body’s natural defense against infection." (PMID 40612057, 2025). "Thirdly, the BChE activity assay cannot identify the cause of the systemic inflammation (sterile inflammation vs. pathogen-induced infection)." (PMID 31320703, 2019). "miR-155: A Modulator of BChE in Immune Responses and Infections - miR-155 plays a pivotal role in regulating immune responses and has been implicated in the modulation of BChE activity during Toxoplasma gondii infection." (PMID 40612057, 2025). "The relationship between BChE, inflammatory response, infection and liver function has been gradually recognized." (PMID 39812044, 2025). "This suggests that miR-155 actively downregulates BChE as part of the inflammatory response to infection." (PMID 40612057, 2025). "The interplay between miR-155 and BChE highlights a potential mechanism through which inflammation and organ-specific damage are exacerbated during infection." (PMID 40612057, 2025). "It is also reported that various clinical conditions such as chronic and acute hepatic dysfunction, inflammation, and infection decrease serum BChE levels." (PMID 39554341, 2024). "Interestingly, in mice treated with sulfamethoxazole-trimethoprim (SMX-TMP), miR-155 levels gradually return to baseline by day 20 post-infection, allowing BChE activity level to recover." (PMID 40612057, 2025). "This way, infection and inflammation are among the risk factors for SIDS and may also contribute to dysregulated BChE levels in cases of SIDS." (PMID 39766923, 2024). "Second, infection and inflammation can affect serum levels of BChE." (PMID 29736152, 2018). "Since low BChE reflects poor immune status, increased inflammation, infections, and poor nutrition of patients, we hypothesize that BChE may be a potential biomarker for HIV/AIDS patients." (PMID 29736152, 2018).
metabolic disorders (8 papers, 2017 to 2025). "The inhibitory effects of ML extract on AChE, BChE, and α‐glucosidase enzymes were also investigated, demonstrating the therapeutic potential of mango leaves in addressing neurodegenerative and metabolic diseases." (PMID 40351366, 2025). "The regulatory effects of fatty acids on BChE and AChE emphasize their potential as therapeutic targets for neurological and metabolic diseases." (PMID 40116876, 2025). "The observed inhibition effects on BChE and α‐glucosidase indicate the important role of MLs in therapeutic applications related to both neuroprotection and metabolic disorders." (PMID 40351366, 2025). "This study offers a foundation for further exploration of BChE’s role in lipid metabolism and its implications for neurodegenerative and metabolic diseases." (PMID 40116876, 2025). "Thus, the precise role of BChE in systemic glucose metabolism and metabolic diseases is still unclear." (PMID 40243328, 2025). "Among its constituents, spathulenol emerged as a key bioactive compound, demonstrating strong binding affinities with multiple therapeutic targets such as AChE, BChE, α-glucosidase, and α-amylase, suggesting its potential as a dual-action agent in managing neurodegenerative and metabolic disorders." (PMID 41191233, 2025). "This suggests that the excess fat tissue itself is not adeterminant factor for the increase in BChE activity, and that a metabolic disorder withan unfavorable lipid profile is more important in this regard." (PMID 28497838, 2017).
cardiovascular disease (7 papers, 2014 to 2025). "This evidence emphasizes the dual role of BChE as a biomarker for cardiovascular risk and a therapeutic target in treating metabolic and cardiovascular diseases." (PMID 40612057, 2025). "Interestingly, BChE activity is negatively correlated with cardiovascular mortality and seems to be a predictor of cardiovascular disease prognosis." (PMID 37941017, 2023).
adenocarcinoma (3 papers, 2017 to 2024). A common cancer characterized by the presence of malignant glandular cells. "The aim of this study was to investigate the prognostic value of pretherapeutic BChE levels in patients with resectable adenocarcinoma of the gastroesophageal junction (AEG), treated with or without neoadjuvant therapy." (PMID 37280384, 2023). "Therefore, the current analysis aimed to evaluate the prognostic role of pretherapeutic serum BChE levels in patients with resectable adenocarcinoma of the esophagus and the gastroesophageal junction." (PMID 37280384, 2023).
infectious disease (3 papers, 2019 to 2025). A disorder directly resulting from the presence and activity of a microbial, viral, or parasitic agent in humans. "Lower levels of butyrylcholinesterase (BChE), a non-specific cholinesterase enzyme, have been correlated with infectious diseases and septic shock, with ongoing research into the utility of BChE in multiple systemic inflammatory conditions." (PMID 40230734, 2025).
psychiatric disorder (3 papers, 2020 to 2025). A disorder characterized by behavioral and/or psychological abnormalities, often accompanied by physical symptoms. "This study provides new insight into the regulatory role of BChE in cognition and suggests potential target for stress-related psychiatric disorder such as PTSD where patients experience fear after exposure to severe life-threatening traumatic events." (PMID 33061920, 2020). "The genes BCHE and CCS were implicated in multiple psychiatric disorder–cognition associations." (PMID 40002349, 2025).
renal diseases (3 papers, 2014 to 2025). "Low BChE activity is associated with hepatic and renal diseases." (PMID 27843744, 2016). "Although many acquired conditions may affect BChE activity (liver or renal diseases, malnutrition, pregnancy, malignancy), BChE deficiency is mainly due to mutations in the BCHE gene (MIM 177400)." (PMID 25054547, 2014).
inflammation (2 papers, 2022 to 2023). Aberrant reaction of the microcirculation characterized by movement of fluid and leukocytes from the blood into extravascular tissues. "In addition, inhibition of BCHE is considered to reduce immunity through the cholinergic anti-inflammatory pathway, although its role in lung inflammation is still unknown." (PMID 35967794, 2022).
autosomal recessive disease (1 paper, 2022). Autosomal recessive form of disease. "Our data suggests a higher risk for some autosomal recessive diseases in Acadians, notably those associated with AIRE, BCHE, ETFDH, RAPSN and SLC17A5 (2 variants)." (PMID 35488281, 2022).
bacterial infections (1 paper, 2022). "Combined use of BChE and MR-proADM for the detection of a systemic inflammation caused by bacterial infection revealed an AUC of 0.762 with a 95% CI of 0.649–0.875." (PMID 35883545, 2022). "This study has identified plasmatic BChE activity as an efficient and highly sensitive point-of-care testing tool for the detection of bacterial infections following liver transplantation." (PMID 35883545, 2022). "After identifying the presence of bacterial infection, we measured the BChE activity in transplanted patients and compared these values to those obtained from the matched unobtrusive transplanted patients." (PMID 35883545, 2022). "Here, we tested whether reduced BChE activity correlates with bacterial infections in transplanted patients." (PMID 35883545, 2022). "Indeed, BChE activity was significantly lower in patients with a bacterial infection as compared to the matched unobtrusive patient group." (PMID 35883545, 2022). "Furthermore, reduced BChE and increased MR-proADM activity could indicate early post-transplantation bacterial infections, whereas conventional inflammatory biomarkers showed no diagnostic efficacy within the observation period." (PMID 35883545, 2022). "Importantly, BChE activity change is not specific for bacterial infections." (PMID 35883545, 2022).
central nervous system diseases (1 paper, 2021). "This study explores the physiological functions of BChE in the central nervous system and the application prospect of BChE inhibitor (R)-bambuterol in the treatment of central nervous system diseases." (PMID 34062954, 2021).
genetic disease (1 paper, 2016). "We focused our analysis on two apparent high impact mutations in genes known to be related to human genetic disease, ribonuclease L (RNASEL) in animal ON12033 (chr01: 184268143) and BChE in animal ON22186 (chr03:69751554)." (PMID 26935327, 2016).
heart disorder (1 paper, 2025). A disease involving the heart and/or pericardium. "BChE And Cardiovascular System - BChE is involved in both the normal function of the heart and heart disorders, specially through its roles in inflammatory regulation, neural regulation, and lipid metabolism." (PMID 40612057, 2025).
hematologic malignancies (1 paper, 2019). "Considering only the patients who underwent allogenic HSCT for hematologic malignancies, BChE activity value ≤ 1799 U/L maintained a good predictive performance for severe liver damage with AUC = 0.761 and 95% CI = 0.673–0.835 (p < 0.001), sensitivity 63.2% and specificity 84.7%." (PMID 31185690, 2019).
BCHE also shares sentences with these, for which no sentence is quoted: cognitive disorder (5 papers); Clear Cell Renal Cell Carcinoma (3); Parkinson (3); skin disorder (3); sudden infant death syndrome (3); acute renal failure (2); alcohol abuse (2); Ataxia (2); breast carcinoma (2); Cachexia (2); endometriosis (2); liver fibrosis (2); Neurodegeneration (2); ovarian carcinoma (2); renal failure (2); type 1 diabetes mellitus (2); acanthosis nigricans (1); acne (1); acute coronary syndrome (1); acute GVHD (1); acute respiratory distress syndrome (1); adenocarcinoma of the gastroesophageal junction (1); age (1); allergic disease (1); Arrhythmia (1); Atrophy (1); autism spectrum disorder (1); autonomic dysfunction (1); bacteremia (1); bipolar disorder (1).
A further 52 diseases each share a sentence with BCHE in 1 paper.